RPS28 (ribosomal protein S28)
Description:
Component of the small ribosomal subunit. The ribosome is a large ribonucleoprotein complex responsible for the synthesis of proteins in the cell. Part of the small subunit (SSU) processome, first precursor of the small eukaryotic ribosomal subunit. During the assembly of the SSU processome in the nucleolus, many ribosome biogenesis factors, an RNA chaperone and ribosomal proteins associate with the nascent pre-rRNA and work in concert to generate RNA folding, modifications, rearrangements and cleavage as well as targeted degradation of pre-ribosomal RNA by the RNA exosome.
Synonyms: S28; eS28; DBA15
Tractability: Small molecule: an approved drug acts on it; a structure with a bound ligand is known; a high-quality ligand is known. PROTAC: ubiquitination databases record sites on it; its protein half-life has been measured; a small molecule that binds it is known. Other modalities: a drug acting on it is in phase 2 or 3 trials.
Target class: Other cytosolic protein
Gene: Protein-coding gene on chromosome 19 (8,320,900 to 8,323,567, forward strand). Ensembl gene ENSG00000233927.
Subcellular location: Cytoplasm, cytosol; Cytoplasm; Rough endoplasmic reticulum; Nucleus, nucleolus
Subcellular location (Human Protein Atlas): Cytosol
Pathways (Reactome):
Metabolism of proteins: Eukaryotic Translation Termination; Formation of a pool of free 40S subunits; Formation of the ternary complex, and subsequently, the 43S complex; GTP hydrolysis and joining of the 60S ribosomal subunit; L13a-mediated translational silencing of Ceruloplasmin expression; PELO:HBS1L and ABCE1 dissociate a ribosome on a non-stop mRNA; Peptide chain elongation; Ribosomal scanning and start codon recognition; SRP-dependent cotranslational protein targeting to membrane; Translation initiation complex formation; ZNF598 and the Ribosome-associated Quality Trigger (RQT) complex dissociate a ribosome stalled on a no-go mRNA
Disease: SARS-CoV-1 modulates host translation machinery; SARS-CoV-2 modulates host translation machinery; Viral mRNA Translation
Metabolism of RNA: Major pathway of rRNA processing in the nucleolus and cytosol; Nonsense Mediated Decay (NMD) enhanced by the Exon Junction Complex (EJC); Nonsense Mediated Decay (NMD) independent of the Exon Junction Complex (EJC)
Cellular responses to stimuli: Response of EIF2AK4 (GCN2) to amino acid deficiency
Developmental Biology: Regulation of expression of SLITs and ROBOs
Metabolism: Selenocysteine synthesis
Gene Ontology:
Molecular function: protein binding; RNA binding; structural constituent of ribosome
Biological process: cytoplasmic translation; ribosomal small subunit biogenesis; ribosome biogenesis; rRNA processing; maturation of SSU-rRNA; ribosomal small subunit assembly; translation
Cellular component: cytosolic small ribosomal subunit; extracellular exosome; ribosome; small ribosomal subunit; small-subunit processome; cytoplasm; cytoplasmic side of rough endoplasmic reticulum membrane; cytosol; nucleoplasm; rough endoplasmic reticulum; cytosolic ribosome; nucleolus; synapse
Genetic constraint (gnomAD): Loss-of-function variants: 2 observed, 6.93 expected, observed/expected ratio (o/e) 0.29, 90% interval 0.12 to 0.91. That is too few expected variants to judge how well the gene tolerates losing a copy. Missense variants: 35 observed, 82.46 expected, observed/expected ratio (o/e) 0.42, 90% interval 0.32 to 0.56. Synonymous variants: 41 observed, 32.65 expected, observed/expected ratio (o/e) 1.26, 90% interval 0.98 to 1.63.
Homologues: Orthologues: dog RPS28 (100% identical), macaque RPS28 (100% identical), mouse Rps28 (100% identical), zebrafish rps28 (96% identical), tropical clawed frog rps28 (78% identical), Caenorhabditis elegans rps-28 (77% identical), Drosophila melanogaster RpS28b (75% identical), Drosophila melanogaster RpS28a (68% identical).
Diseases named in the same sentence as RPS28 in open-access papers:
RPS28 is named in the same sentence as 23 diseases in open-access papers, as found by Europe PMC text mining. Sharing a sentence is not in itself a finding about the gene and the disease. The quoted sentences say what the papers report.
hepatocellular carcinoma (3 papers, 2021 to 2025). A malignant tumor that arises from hepatocytes. "Using an antisense oligonucleotide to block tRF-3LeuCAG prevents it from binding RPS28 mRNA, resulting in diminished ribosome biogenesis and apoptosis of hepatocellular carcinoma cells." (PMID 33391486, 2021). "A tRF-3 from tRNA-Leu-CAG induces apoptosis via binding to ribosomal protein S28 (RPS28) and RPS15, and tRF-3 targets the coding sequence (CDS) and 3′-UTR of RPS28 mRNA, enhances RPS28 expression, and increases 40S ribosomal subunits in hepatocellular carcinoma in mice." (PMID 36547066, 2022). "In an in vivo hepatocellular carcinoma model, LeuCAG3′tsRNA was shown to enhance the translation of ribosomal protein S28 (RPS28) mRNA, promoting cell proliferation, whereas its inhibition reduced RPS28 expression, impaired ribosome assembly, and induced apoptosis." (PMID 41244208, 2025).
bone marrow failure syndrome (2 papers, 2018 to 2022). "RPS28 downregulated gene was causally associated with human bone marrow failure syndromes or hematologic malignancies." (PMID 36077467, 2022). "Many of the differentially downregulated ribosomal genes (e.g. RPS19, RPS28) have been causally associated with human bone marrow failure syndromes and hematologic malignancies." (PMID 29954325, 2018).
ischaemic stroke (2 papers, 2022 to 2024). "However, the dysfunction of RPS15A, RPS6, and RPS28 in females with ischemic stroke patients has never been reported." (PMID 35432523, 2022).
osteosarcoma (2 papers, 2022). A usually aggressive malignant bone-forming mesenchymal neoplasm, predominantly affecting adolescents and young adults. "Both univariate and LASSO Cox regression analyses were conducted on screened module genes to identify 5 GCSRGs (RPS28, MCAM, EN1, TRAM2, and VEGFA) constituting a prognostic signature for osteosarcoma patients." (PMID 36618348, 2022).
COVID-19 (1 paper, 2022). A disease caused by infection with severe acute respiratory syndrome coronavirus 2. "Among them, three (RPS28, RPLP2, and PDE12) had matching risk factor genes showing consistent patterns, i.e., transcriptional upregulations increased the COVID-19 mortality risk." (PMID 35547187, 2022).
Diamond-Blackfan anaemia (1 paper, 2022). "Mutations in RPS19, RPS28, RPS10 and RPS5 result in the ribosomopathy Diamond-Blackfan anaemia." (PMID 34283226, 2022).
dilated cardiomyopathy (1 paper, 2023). Cardiomyopathy which is characterized by dilation and contractile dysfunction of the left and right ventricles. "Interestingly the lncRNA ribosomal protein S28 (RPS28), downregulated in fetal male LV with prenatal T is also one of the genes reported to be differentially regulated in end stage dilated cardiomyopathy in human LV56." (PMID 36792653, 2023).
endometriosis (1 paper, 2016). The growth of functional endometrial tissue in anatomic sites outside the uterine body. "Among the selected genes, SNORD116, RPLP2, RPL38 and 40S ribosomal protein S28 (RPS28) were most elevated ones in endometriosis patients, which was consistent with our in vitro experimental findings using miR196a2-C vector." (PMID 27741504, 2016).
lung adenocarcinoma (1 paper, 2014). A carcinoma that arises from the lung and is characterized by the presence of malignant glandular epithelial cells. "Among them, only three genes (CTIF, FAU, and RPS28) are significantly down-regulated in tumors, implying NMD may not be inhibited in lung adenocarcinoma and thus cannot explain the large amount of intron retentions in tumors." (PMID 24646369, 2014).
melanoma (1 paper, 2023). A malignant, usually aggressive tumor composed of atypical, neoplastic melanocytes. "A study on melanoma found that mutations in ribosomal proteins resulting in the deletion of RPS28 caused greater killing of melanoma cells by CD8+ T cells, indicating the association of RPS28 with CD8+ T cells." (PMID 37007947, 2023).
multiple myeloma (1 paper, 2024). "It is worth mentioning that RPS28 is one out of the nine up-regulated hub genes in multiple myeloma (MM) and also is one out of the seven prognosis-related genes of RNA-binding proteins suggested as a prognosis panel for oral cavity squamous cell carcinoma (OCSCC)." (PMID 38397997, 2024).
Stroke (1 paper, 2024). Sudden impairment of blood flow to a part of the brain due to occlusion or rupture of an artery to the brain. "ELISA detected the expression of C1QBP, RPS28 and RNASEL proteins in stroke patients, and the proportion of neutrophils was significantly increased in the high-risk group." (PMID 39290696, 2024).
cancer (9 papers, 2010 to 2024). A tumor composed of atypical neoplastic, often pleomorphic cells that invade other tissues. "There are few studies on the effect of RPS28 on cancer, and most research results are only predictions generated by bioinformatics and have not been confirmed by corresponding biological experiments." (PMID 36618348, 2022). "However, some researchers have found that reducing the expression of RPS28 protein can reduce the cell viability of HeLa cells and induce tumor cell apoptosis, indicating that RPS28 has a major regulatory function in cancer." (PMID 36618348, 2022). "As for RPS28 (ribosomal proteins S28), it could influence T cell-mediated cancer immunosurveillance by regulating the generation of MHC class I peptide on the cell surface." (PMID 34585646, 2021). "Therefore, the expression of RPS28 can be reduced by inhibiting LeuCAG 3' tsRNA and thereby damaging the 18S rRNA pathway, thus reducing the survival ability of cancer cells and promoting apoptosis of cancer cells." (PMID 38370372, 2024). "Furthermore, adding 3 ́tsRNALeu mimics to cells increased RPS28 protein suggesting that this tsRNA may be important perhaps in increasing the number of ribosomes that are required for enhanced protein synthesis in conditions such as cancer." (PMID 34324497, 2021).
tumor (9 papers, 2022 to 2025). "Increased expression of RPS28 in sporadic CRC is associated with tumor progression, which could become a potential biomarker." (PMID 38542474, 2024). "Lastly, we validated the expression of the five RBRS genes (RPL38, RPS2, RPS14, RPS19, and RPS28) using qRT-PCR on tumor and adjacent normal samples from 12 ccRCC patients at Meizhou Hospital." (PMID 40642093, 2025). "Eight proteins were upregulated in the hippocampus in response to sustained tumour growth, including Psmd6, Rps28, calretinin (Calb2) and Pdcd6." (PMID 40172096, 2025). "In addition, the in vivo injection of 143B cells with a stable RPS28 KD led to smaller tumor volume and weight with inferior KI-67 staining compared to the control group." (PMID 39596100, 2024). "We propose that targeting of RPS28 by members of the MIR-28 family may be one novel aspect of their effectiveness as tumor suppressors." (PMID 38197221, 2024). "Additionally, RPS28 can influence tumor immunosurveillance and regulate T cell killing." (PMID 36618348, 2022). "This suggests that other significantly altered transcripts such as RPS28, CYP4Z1, and IL6ST may represent novel biomarkers or candidate regulators of tumor progression." (PMID 35992327, 2022).
infection (2 papers, 2022 to 2024). The state of being infected such as from the introduction of a foreign agent such as serum, vaccine, antigenic substance or organism. "In contrast, the biological processes downregulated with infection include ribosomal biogenesis (Rpl3, Rpl37, Rps5, Rpl11, Rplp1, Rpl28, Rpl19, Rps28, Rps14)." (PMID 35789215, 2022).
infectious disease (1 paper, 2022). A disorder directly resulting from the presence and activity of a microbial, viral, or parasitic agent in humans. "In the case of the pre-diagnostic markers for CD4+ T cells, the upregulated genes included ribosomal proteins (e.g. RPL39, RPL37, RPS28 and RPS21) that showed enrichments in pathways related to translation and “Infectious disease”." (PMID 35371081, 2022).
RPS28 also shares sentences with these, for which no sentence is quoted: hematologic malignancies (2 papers); breast carcinoma (1); Diamond-Blackfan anemia (1); Neonatal sepsis (1); oral cavity squamous cell carcinoma (1); ovarian carcinoma (1); prostate carcinoma (1).